ARPC1A (actin related protein 2/3 complex subunit 1A)
Diseases named in the same sentence as ARPC1A in open-access papers:
ARPC1A is named in the same sentence as 19 diseases in open-access papers, as found by Europe PMC text mining. Sharing a sentence is not in itself a finding about the gene and the disease. The quoted sentences say what the papers report.
pancreatic cancer (4 papers, 2013 to 2024). "Being a cytoskeletal protein, ARPC1A has been reported to be involved in the regulation of cell migration and invasion in pancreatic cancer." (PMID 23737949, 2013). "ARPC1A, the gene encoding for the p41 subunit of Arp2/3, is frequently overexpressed in pancreatic cancer due to 7q21-q22 gene amplification, and RNA interference experiments show a significant decrease in tumor cell migration and invasion upon ARPC1A and ARPC4 knockdown." (PMID 26345720, 2015).
prostate carcinoma (4 papers, 2019 to 2024). A carcinoma that arises from epithelial cells of the prostate gland. "Previous studies reported that ARPC1A expression was upregulated in prostate cancer, and overexpression promoted lung metastasis of tumor cells." (PMID 38911374, 2024). "They showed that ARPC1A facilitates cytoskeletal formation, invasion, and migration of prostate cancer cells." (PMID 39867911, 2024). "Silencing ARPC1A inhibits migration, invasion, and cytoskeleton formation of prostate cancer cells." (PMID 38911374, 2024). "Actually, we mainly used AR-negative PC-3 and DU-145 for in vitro experiments, so it is indeed unclear whether ARPC1A plays a similar role in AR-positive prostate cancer cells, which is one of the main limitations of this study." (PMID 36814338, 2023). "Given that recent studies have shown glutamine metabolism upregulates ARPC1A in prostate cancer and ASNS is a key enzyme in glutamine metabolism, it may mediate ARPC1A upregulation." (PMID 39867911, 2024).
breast carcinoma (3 papers, 2019 to 2024). "Subsequently, we determined that ARPC1A was predominantly present in the cell junctions and cytoplasm by immunofluorescence in A-431 (human epidermoid carcinoma cell line) and MCF-7 (human breast cancer cells)." (PMID 38911374, 2024). "The following genes were reported to be lower expressed in breast cancer samples of cases compared to controls in two different studies but were reported to be higher expressed in another study: PABPC1, ARPC1A, TXN, TOB1." (PMID 36627894, 2022).
epidermoid carcinoma (2 papers, 2022 to 2024). "Although there is limited evidence on ARPC1A, a study has demonstrated that silencing of actin-related protein 2/3 complex subunit 5 significantly reduced cell motility in squamous cell carcinoma." (PMID 35806375, 2022).
hepatocellular carcinoma (2 papers, 2024 to 2025). A malignant tumor that arises from hepatocytes. "In hepatocellular carcinoma, ARPC1A was shown to be highly expressed and associated with poor prognosis." (PMID 38911374, 2024).
lung adenocarcinoma (2 papers, 2020 to 2024). A carcinoma that arises from the lung and is characterized by the presence of malignant glandular epithelial cells. "Marked suppression of growth, invasion, and migration in lung adenocarcinoma cells is observed when ARPC1A expression is reduced, likely mediated by c-Myc." (PMID 39867911, 2024).
osteosarcoma (2 papers, 2018 to 2019). A usually aggressive malignant bone-forming mesenchymal neoplasm, predominantly affecting adolescents and young adults. "In fact, the overexpression of isoform 1 in osteosarcoma cell lines likewise modulated the expression of genes essential for remodeling the actin cytoskeleton and cell invasion through expression of ARP2 and ARPC1A, which code for proteins of the Arp2/3 complex." (PMID 30845661, 2019).
brain malignant gliomas (1 paper, 2024). "Our GSEA in brain malignant gliomas and single-cell functional analysis revealed a positive correlation between ARPC1A and EMT, as well as critical signaling pathways for proliferation." (PMID 38911374, 2024).
glioblastoma (1 paper, 2024). The most malignant astrocytic tumor (WHO grade IV). "This study aims to investigate the biological role of ARPC1A in various cancers and the regulatory role of ARPC1A in glioblastoma multiforme (GBM)." (PMID 38911374, 2024).
glioma (1 paper, 2024). A benign or malignant brain and spinal cord tumor that arises from glial cells (astrocytes, oligodendrocytes, ependymal cells). "We analyzed common clinical risk factors for glioma, including age, gender, WHO grade, IDH mutation status, 1p19q co-deletion status, and high and low expression of ARPC1A." (PMID 39012280, 2024).
Hypercholesterolemia (1 paper, 2022). An increased concentration of cholesterol in the blood. "Interaction analysis showed that ACTB formed the hub of the revealed network, being involved in many interactions with other accessory proteins (e.g., with upregulated CAP1, WDR1, GSN, RHOA, and ARPC1A), suggesting myocardial cytoskeleton rearrangement in response to hypercholesterolemia." (PMID 35806390, 2022).
metastasis (1 paper, 2023). The spread or migration of cancer cells from one part of the body (where they first appeared) to another. "We found that ARPC1A expression was significantly higher in tumors than that in normal tissues, and was significantly associated with tumor progression and lymph node metastasis." (PMID 36814338, 2023).
cancer (8 papers, 2013 to 2025). A tumor composed of atypical neoplastic, often pleomorphic cells that invade other tissues. "Actin-related protein 2/3 complex subunit 1A (ARPC1A) is implicated in several cancers due to its critical role in regulating actin polymerization." (PMID 38911374, 2024). "Given ARPC1A’s high expression across cancer types and its substantial diagnostic value relative to other subunits, it was selected for further investigation." (PMID 39867911, 2024). "Given its high expression in most tumor types and significant diagnostic value, we selected ARPC1A for further pan-cancer functional analysis and experimental validation." (PMID 39867911, 2024). "ARPC1A’s potential as a biomarker for predicting immune responses across various cancers is suggested by further analysis of its association with immune cell infiltration and immune-related regulatory factors." (PMID 39867911, 2024). "In summary, our results highlight a strong association between elevated ARPC1A expression, oxidative phosphorylation metabolism, proliferation, and immune suppression in cancer." (PMID 39867911, 2024). "To reveal the genomic mutations of ARPC1A in cancer, we analyzed the mutation frequency of ARPC1A in tumors." (PMID 38911374, 2024). "ARPC1A expression was up-regulated in most cancer tissues and was associated with poorer prognosis." (PMID 38911374, 2024). "Our study leveraged public databases and bioinformatics tools to comprehensively explore the biological mechanisms of ARPC1A in a pan-cancer context, its association with the immune microenvironment and chemotherapy sensitivity, and its potential as a biomarker for predicting immunotherapy response." (PMID 39867911, 2024). "In summary, our study supports targeting Arp2/3 complex subunits as a novel anticancer strategy, highlights the prognostic and diagnostic value of ARPC1A across cancers, and emphasizes the connections between ARPC1A, oxidative phosphorylation, and tumor immunity." (PMID 39867911, 2024). "We conducted an additional assessment of ARPC1A’s potential impact on cancer immunotherapy by analyzing cancer immune cycle activity scores using the TIP database." (PMID 39867911, 2024). "Mainly, the expression differences of ARPC1A in its involvement in the cancer promotion in LGG specifically from the TCGA and CGGA datasets." (PMID 39012280, 2024). "A heatmap analysis was performed to explore the relationship between ARPC1A and immune-related molecules across cancers." (PMID 39867911, 2024). "Initially, we evaluated the relationship of ARPC1A mRNA levels with a range of functional proteins in different cancers by utilizing the TCPA database." (PMID 39867911, 2024). "Our study offers novel insights into targeting Arp2/3 complex subunits as an anti-cancer strategy and underscores the potential of ARPC1A as a novel biomarker for tumor diagnosis, prognosis, and the prediction of immune therapy responses." (PMID 39867911, 2024). "The Arp2/3 complex subunits, particularly ARPC1A, are frequently overexpressed in a majority of cancers, correlating with poor prognostic outcomes and demonstrating significant diagnostic utility." (PMID 39867911, 2024). "Specifically, ARPC1A appears to enhance cell proliferation and oxidative phosphorylation across various cancers through the regulation of c-Myc expression." (PMID 39867911, 2024). "We analyzed the expression differences, prognostic value, mutations, immune infiltration, immune microenvironment, and single-cell level correlations of ARPC1A in various cancers." (PMID 38911374, 2024). "Overall, we explored the expression and prognostic value of ARPC1A in pan-cancer and GBM from multiple perspectives, highlighting its great potential for application in clinical diagnosis." (PMID 38911374, 2024). "Next, ARPC1A is involved in the proliferation of cancer cells, and its involvement in apoptosis was also described through knockout experiments." (PMID 39012280, 2024).
cancer (continued). "The results revealed that ARPC1A was positively correlated with M0-, M1-, and M2-type macrophages in most cancers, whereas it was negatively correlated with naive B cells." (PMID 38911374, 2024). "This research offers valuable insights into the role of ARPC1A in cancer development, particularly as a potential therapeutic target for GBM." (PMID 38911374, 2024). "The relationship of ARPC1A mRNA expression with TMB/MSI across various cancer types was examined, taking into account the significance of PD-L1, MSI, and TMB as key biomarkers for immunotherapy." (PMID 39867911, 2024). "In this study, we conducted a comprehensive pan-cancer analysis of ARPC1A utilizing multiple public databases and experimental validation." (PMID 38911374, 2024). "Gene set enrichment analysis was performed for the relevant datasets pertinent to the expression of ARPC1A to elucidate the cancer-promoting pathways involved in the LGG through KEGG and GO analysis." (PMID 39012280, 2024). "The findings underscore ARPC1A’s significance in multiple cancers, pointing to the need for in-depth studies on its molecular mechanisms, targeted treatments, and combination therapy approaches." (PMID 39867911, 2024). "In conclusion, these findings emphasize the connection of Arp2/3 complex components, particularly ARPC1A, with cancer progression, reinforcing their potential as biomarkers for cancer diagnosis and prognosis." (PMID 39867911, 2024). "Heatmap showed that substantial activation of oxidative phosphorylation and signaling pathways related to cell proliferation, such as DNA repair, TORC1, MYC and E2F, was correlated with elevated ARPC1A expression in cancer patients." (PMID 39867911, 2024). "Specifically, ARPC1A mRNA levels had high sensitivity and specificity for diagnosing 12 cancer types (AUC > 0.7)." (PMID 39867911, 2024). "Western blotting was used to examine the involvement of the cancer-promoting activity of ARPC1A through MAPK signaling." (PMID 39012280, 2024). "Next, we examined ARPC1A expression in human PCa cell lines and found it to be much higher in cancer lines (22Rv1, DU-145, PC-3 and LNCaP), when compared with BPH-1 normal human prostate epithelial cells." (PMID 36814338, 2023). "In prostate cancer, ARPC1A is transcriptionally regulated by STAT3: It not only supplies energy to cancer cells by enhancing oxidative phosphorylation but also maintains an immunosuppressive microenvironment by inhibiting ferroptosis—creating favorable conditions for cancer progression." (PMID 41332982, 2025). "An examination of the seven stages of the immune cycle in groups with elevated versus reduced ARPC1A expression revealed that increased ARPC1A levels correlated with lower TIP scores across most cancer types, suggesting possible immunosuppressive effects within the TME." (PMID 39867911, 2024). "However, additional studies are required to investigate and elucidate the specific molecular mechanisms through which ARPC1A regulates cancer progression and tumor immunity." (PMID 39867911, 2024). "Interestingly, we observed that ARPC1A expression in the EPIC algorithm was negatively correlated with B cells of most cancers." (PMID 38911374, 2024). "This study aims to investigate the clinical relevance of Arp2/3 complex subunits, particularly ARPC1A, in pan-cancer, and to further analyze the potential biological mechanisms of ARPC1A, as well as its association with immune infiltration and chemotherapy drug sensitivity." (PMID 39867911, 2024). "However, the role of ARPC1A has been mainly limited to individual tumor types, necessitating comprehensive studies encompassing pan-cancer datasets." (PMID 38911374, 2024). "Clinical trials targeting ARPC1A as a potential therapeutic combination with immune therapies could open new avenues for cancer immunotherapy." (PMID 39867911, 2024).
cancer (continued). "Given that prior GSEA analysis suggested ARPC1A may be involved in immune suppression, we compared immune scores among patients with elevated and reduced ARPC1A expression across 32 cancer types." (PMID 39867911, 2024). "From a pan-cancer perspective, ARPC1A expression was positively correlated with VEGFB and CD276." (PMID 38911374, 2024). "The different expression patterns of ARPC1A in various cancers suggest that ARPC1A may play specific functional roles in different tumors." (PMID 38911374, 2024). "However, ARPC1A’s role across different cancers requires further clarification." (PMID 39867911, 2024). "Importantly, data from all three databases indicate that ARPC1A is associated with resistance to gefitinib, implying that targeting ARPC1A could improve treatment outcomes for gefitinib-resistant cancer patients." (PMID 39867911, 2024). "The findings above suggest that ARPC1A may contribute to immune suppression in these cancers." (PMID 39867911, 2024). "Both analyses showed that Arp2/3 complex components’ mRNA levels are notably increased in BRCA, with ARPC1A and ARPC1B upregulated across most cancer types." (PMID 39867911, 2024). "Expression of the mitochondria-related genes including SLBP, ARPC1A, and TOMM34 (TCGA database) were significantly higher in cancer tissues than the normal tissues." (PMID 39012280, 2024). "However, the exact mechanism of ARPC1A in cancer remains unclear." (PMID 38911374, 2024). "A strong positive correlation between ARPC1A mRNA levels and ASNS was observed across six cancer types, including LUAD." (PMID 39867911, 2024). "Moreover, ARPC1A, ARPC1B, and ARPC5 demonstrated significant copy number amplification in most cancer types." (PMID 39867911, 2024). "None of the predicted target genes of ARPC1A have been previously reported in the context of cancer." (PMID 23737949, 2013). "ARPC1A exhibited significant negative correlations with immune-related genes (MHC, immunosuppressors, immune stimulators, chemokines) in most cancer types." (PMID 39867911, 2024). "The analysis indicated a negative correlation between ARPC1A mRNA expression levels and the abundance of B cells and CD8+ T cells in most cancer types, suggesting that ARPC1A may suppress the TME." (PMID 39867911, 2024).
tumor (7 papers, 2015 to 2025). "We have confirmed ARPC1A overexpression in PCa tissues and also its role in cellular processes associated with tumor invasion and spread." (PMID 36814338, 2023). "In line with earlier localization findings, a significant positive correlation was observed between ARPC1A expression levels and the tumor cell content within the spots." (PMID 39867911, 2024). "Quantification showed higher ARPC1A expression in malignant regions, suggesting predominant expression in tumor cells." (PMID 39867911, 2024). "Analysis of tissue sections from LUAD and LUSC and the spatial distribution of major cell types revealed that ARPC1A expression closely correlates with the localization of tumor cells." (PMID 39867911, 2024). "Both GSEA and single-cell sequencing have revealed that ARPC1A promotes tumor proliferation and epithelial-mesenchymal transition." (PMID 38911374, 2024). "In conclusion, the modulation of ARPC1A expression shows promise for shaping the immune microenvironment and discovering new anti-tumor therapeutic strategies." (PMID 38911374, 2024). "In single-cell tumor samples, ARPC1A expression was higher in OV, UCEC, and TNBC compared to other tumors." (PMID 38911374, 2024). "Second, the role of ARPC1A in the tumor immune microenvironment suggests its potential as a target for immune therapy." (PMID 39867911, 2024). "To examine the function of ARPC1A in tumor progression, we explored the expression of ARPC1A in different stages of tumors." (PMID 38911374, 2024). "To evaluate the correlation between ARPC1A mRNA levels and tumor prognosis, we downloaded OS, DSS, DFI, and PFI data of patients with different tumors." (PMID 38911374, 2024). "At the single-cell level, we analyzed the expression of ARPC1A in tumor single-cell samples." (PMID 38911374, 2024). "Finally, small molecule inhibitors or antibodies targeting ARPC1A could become powerful tools for combating tumor metastasis." (PMID 39867911, 2024). "However, the exact mechanism by which ARPC1A affects tumor development remains unknown." (PMID 38911374, 2024). "In vivo, ARPC1A overexpression promoted lung metastasis of PCa, but had no efffect on tumor growth." (PMID 36814338, 2023). "ARPC1B, but not ARPC1A, was overexpressed in a majority of tumours." (PMID 30971746, 2019).
ARPC1A also shares sentences with these, for which no sentence is quoted: lung carcinoma (3 papers); acute myeloid leukemia (1); Fanconi anemia (1); non-small cell lung carcinoma (1); Wiskott-Aldrich syndrome (1).